INS (insulin)
Diseases named in the same sentence as INS in open-access papers (continued):
Sharing a sentence is not in itself a finding about the gene and the disease.
Insulin resistance (continued). "Thus, we propose that the insulin sensitizing effect of BME on the TNF-α-treated enterocytes may be a result of its anti-inflammatory function, ameliorating inflammation-induced insulin resistance." (PMID 33746602, 2021). "Briefly, caloric loss by SGLT2 inhibition may decrease plasma glucose without increasing insulin secretion, which may reduce body weight and result in an improvement of insulin resistance." (PMID 33922546, 2021). "The term “insulin resistance” should carefully used as impaired insulin sensitization occurs in the liver, as well as in skeletal muscle and adipocytes; therefore, we could not determine which organ induced insulin resistance in the present study." (PMID 34321567, 2021). "However, when fed an HFS diet, adG6AKO mice manifested an increased fasting blood glucose level, glucose intolerance, and insulin resistance without any change in fasting or glucose-induced serum insulin levels compared with control mice." (PMID 33428938, 2021). "Furthermore, ERK proteins control insulin resistance in in vitro studies by the effect of c-Jun activation domain-binding protein-1 (JAB1), activated under chronic inflammation, increased in insulin-resistant states, and mimicked using palmitic acid in hepatocytes." (PMID 34069890, 2021). "Increased insulin secretion might effectively decrease glycemia levels or not, depending on the grade of insulin resistance." (PMID 35010932, 2021). "By doing OGTT combined with insulin measures we were able to assess insulin function related to secretion (HOMA-B) and resistance (HOMA-IR), and investigate whether insulin resistance is central/hepatic (based on fasting samples) or systemic/muscular (based on kinetics during OGTT)." (PMID 34657634, 2021). "The occurrence of insulin resistance (decreased glucose uptake) appears as early as 24 h after denervation, although without alteration in the IR ability to bind insulin or transfer downstream signaling to PI3K and Akt, and it is followed by a marked GLUT-4 downregulation 3 d after denervation." (PMID 33401549, 2021). "Fourth, insulin levels were not measured, which might have been important to clarify a possible involvement of copeptin in insulin resistance." (PMID 33882083, 2021). "Moreover, tryptophan-derived metabolites produced by the gut microbiota was found to control the expression of the miR-181 family, which promote the development of insulin resistance and WAT inflammation in obese mice and humans, to regulate energy expenditure and insulin sensitivity." (PMID 34502047, 2021). "Furthermore, since the liver functions as an endocrine organ in systemic insulin sensitivity, whether hepatic GHR is can affect hepatokine-regulated interorgan communication, thereby being involved in the pathogenesis of insulin resistance is unknown." (PMID 34373742, 2021). "During insulin resistance, to ensure that the blood sugar level stays within the normal level, islet B cells in pancreatic islets will secrete more insulin to make up for the lack of the hypoglycemic ability of unit insulin so as to ensure a normal blood sugar level." (PMID 34122100, 2021). "Total cholesterol and insulin concentrations and HOMA-IR values were found to be higher in the obese group as compared to the non-obese group (p < 0.05), and the volunteers from the obese group were diagnosed with insulin resistance according to the HOMA-IR assessment (3.02 ± 0.46)." (PMID 33573276, 2021). "Studies on knockout animals for AKT showed that the absence of this enzyme in the liver induced severe insulin resistance, glucose intolerance, and a reduction in hepatic lipid synthesis, thus supporting the importance of its activation to improve insulin sensitivity." (PMID 34639123, 2021).
Insulin resistance (continued). "In the early stage of T2DM, the insulin level is abnormally increased, which indicates a cellular signaling impairment rather than an alteration in insulin production, because of reduced peripheral insulin receptor sensitivity and signaling which results in insulin resistance." (PMID 34564146, 2021). "We instead observed a negative correlation between insulin sensitivity and adiponectin concentrations; this hormone is indeed known to have a pivotal role in combatting the development of insulin resistance and metabolic diseases by increasing tissue fat oxidation." (PMID 34649266, 2021). "While insulin resistance, depicted in this study by increased hemoglobin A1c and total daily dose of insulin, worsened in the non-remitters, the remitters remained insulin sensitive and required smaller doses of insulin to maintain glycemia compared to the non-remitters." (PMID 34899592, 2021). "For years, whether the FA oxidation alteration (mitochondrial dysfunction) is the trigger or not of insulin signaling impairment inducing insulin resistance onset was the subject of extensive discussions." (PMID 33844166, 2021). "However, effects on insulin resistance are yet to be elucidated, and RT has been established to be effective in insulin resistant, but not in healthy, older subjects." (PMID 34371972, 2021). "Furthermore, an insulin tolerance test (ITT) revealed a decreased response to exogenous insulin in Ad-hPER3 mice, indicating that increased hPER3 expression aggravated the development of high-fat diet-induced insulin resistance." (PMID 33741899, 2021). "Interestingly, in diet‐induced obese mice already exhibiting basal hyperinsulinemia and systemic insulin resistance, IH did not exert additional systemic metabolic alterations, nor on cardiac insulin signaling, nor on cardiac remodeling and function." (PMID 33682327, 2021). "Sympathetic activity halts insulin secretion in islet beta cells, leading to OSAS patients often displaying impaired insulin sensitivity and increased plasma glucose levels, while studies have shown a significant statistical relationship between the severity of OSAS and insulin resistance." (PMID 35004785, 2021). "While the interventions resulted in a reduction in sedentary time, an increase in moderate-to-vigorous physical activity (MVPA) and a reduction in neonatal adiposity, these lifestyle changes did not result in improvement in glucose or insulin concentrations or insulin resistance." (PMID 32661292, 2021). "One article showed that the increase of long-chain acylcarnitine in circulation can interfere with insulin signal transduction in cell membranes, which is related to the occurrence and development of insulin resistance, but the exact mechanism of action has not yet been elucidated." (PMID 34194524, 2021). "However, unlike the liver-specific LRP1 knockout mice, the impairment of hepatic insulin signaling did not further exacerbate diet-induced hyperglycemia, hyperinsulinemia, and insulin resistance." (PMID 33500241, 2021). "While primarily considered a pro-inflammatory marker, IL-1β also influences insulin secretion and insulin resistance in mice, and could therefore play a primarily metabolic role in fasting-adapted NES, which display insulin resistance." (PMID 34744798, 2021). "Lastly, insulin level data were not available; thus, insulin resistance and insulin sensitivity could not be evaluated." (PMID 35069433, 2021). "Accumulations of DAG, triacylglycerol, and free FAs in non-adipose tissues correlate strongly with insulin resistance, and increases in released, free fatty acids may block insulin signal transduction and contribute to MetSyn." (PMID 34940446, 2021). "No more than five trials consisted of insulin and insulin resistance (HOMR)." (PMID 34543302, 2021).
Insulin resistance (continued). "However, in a mouse model of diet-induced obesity (DIO) and insulin resistance, SCOPA administration by gavage or supplementation of diet was found to improve insulin sensitivity as measured by homeostatic model assessment for insulin resistance (HOMA-IR) or insulin tolerance test (ITT)." (PMID 35211087, 2021). "Probably, the role of insulin resistance in underpinning PCOS pathogenesis has been too much emphasized since the first report in which a link was hypothesized in between PCOS and defects in insulin/glucose metabolism." (PMID 33889133, 2021). "However, it was observed that overnutrition-mediated activation of IKKβ/NF-κB was activated intracellularly by ER stress and prompted both hypothalamic leptin and insulin resistance through the induction of suppressor of cytokine signaling 3 (SOCS3), an inhibitor of leptin and insulin signaling." (PMID 34957242, 2021). "While these relationships reflect systemic insulin resistance, it is critical to note that brain tissue itself is insulin resistant in AD in subjects who, at the time of death, were without other co-morbidities that feature insulin resistance, such as DM2, obesity or the metabolic syndrome." (PMID 34220427, 2021). "Additionally, the initiation of insulin resistance could decrease AMPK phosphorylation, further increase the expression of Srebp-1c, and eventually suppress the Irs-1-related insulin signaling pathway." (PMID 33936248, 2021). "We could not validate whether the TyG index directly correlated with insulin resistance because the NHIS-HEALS cohort did not contain information on serum insulin levels." (PMID 34735502, 2021). "Modulation of the insulin cascade at the proximal level involving the insulin receptor and IRS1/2 has gained considerable interest for explaining the pathophysiology of lipid-induced insulin resistance, pinpointing these mechanisms as key drivers of metabolic dysfunction in obesity and T2DM." (PMID 34440850, 2021). "In muscle, fat accumulation interferes with insulin-stimulated GLUT4 translocation, and in the liver, non-alcoholic fatty liver (NAFL) is associated with hepatic insulin resistance and enhanced production of VLDL-TG that contributes to the development of atherogenic/diabetic dyslipidaemia." (PMID 33387681, 2021). "Although the central insulin sensitizing effect of P. harmala has not been reported before, a study conducted in 201627 has shown that P. harmala extract mitigated palmitic acid-induced insulin resistance in muscle cells by modulating the p-IRS/p-Akt hub." (PMID 34103557, 2021). "Hence, a rise in body weight, blood glucose level, serum insulin, leptin and resistin levels along with reductions in serum adiponectin levels in HFD and sucrose fed rats indicates the development of obesity induced insulin resistance in them." (PMID 33917607, 2021). "This increased insulin secretion may be an advantage in patients with prediabetes that have still not developed insulin resistance." (PMID 35010932, 2021). "Since in Avy hIAPP mice amyloid formation is triggered by the insulin resistance of these mice, it is very difficult to ascertain whether the improvement in glycemia and amyloid is due to the PBA effect to improve insulin sensitivity or improve β cell function, or both." (PMID 34088954, 2021). "In particular, Smad3 KO-db/db mice developed hyperinsulinemia through the lifetime but not insulin resistance, suggesting that Smad3 might also modulates peripheral glucose metabolism and insulin action in a unique manner." (PMID 33456576, 2021). "Furthermore, there was an increase in body weight, liver weight, liver index, Lee’s index, total cholesterol (TC), triglyceride (TG), alanine aminotransferase (ALT), aspartate aminotransferase (AST), fasting blood glucose (FBG) level, insulin level (FINS), and insulin resistance level (HOMA-IR)." (PMID 33691721, 2021).
Insulin resistance (continued). "We performed this study to evaluate and compare the level of insulin, insulin resistance, androgen, and HMWA between obese and non-obese women with PCOS and in four different PCOS phenotypes; in addition, we investigated the relationship between HMWA and the androgen level." (PMID 33750349, 2021). "Finally, our results show that the molecular origins of insulin resistance and hyperinsulinaemia, which are observed in insulin-resistant individuals, are potentially explained by the effects of LCAC on the insulin signalling pathway in insulin-secreting cells." (PMID 34208786, 2021). "However, a previous study including women aged 30–64 years old found no indication of higher insulin or insulin resistance among 223 MCS cases compared to 194 controls." (PMID 34886380, 2021). "Reduced plasma phosphatidylcholine levels in our study were also seen in normoglycemic early overnutrition HFO mice, and all mice exhibited similar insulin sensitivity, suggesting that alterations were not a secondary response to hyperglycemia or insulin resistance." (PMID 34234216, 2021). "The concept of insulin resistance emerges when insulin levels, whether elevated or within normal range, are associated with a diminished metabolic response or sensitivity." (PMID 33967682, 2021). "This insulin resistance does not impair insulin or AMPK signaling in muscle and subcutaneous fat." (PMID 34220716, 2021). "Finally, although we considered the effect of glucose tolerance status by DM status, we did not adjust for insulin resistance status because of the lack of serum insulin levels." (PMID 33800924, 2021). "The other is that α cells are not regulated by insulin, that is, insulin resistance exists." (PMID 34751249, 2021). "Similarly, vascular insulin resistance is clearly present in T1D15, and, in middle-aged individuals with T1D, steady-state insulin mediated glucose uptake strongly correlates with microvascular insulin responsiveness." (PMID 34075130, 2021). "So, an increase in HOMA-IR of STZ-60 could be due to chronic reducing production of insulin by damaged β-cell, rather than insulin resistance itself." (PMID 33525535, 2021). "In animal models of obesity and insulin resistance it was shown that the inhibition of FABP4 protein in macrophages reduces inflammatory cytokines (MCP-1, IL-1β, IL-6 and TNFα) and the formation of atherosclerotic lesions and foam cells and improves insulin sensitivity." (PMID 34834808, 2021). "Notably, lipogenic effects of insulin, unlike its effects on glucose uptake, have been reported to be maintained in individuals who have insulin resistance." (PMID 33917005, 2021). "Interestingly, under obesity and insulin resistance, a long-term increase in insulin levels can also lead to an increase in hypothalamic NPY levels, indicating that hypothalamic NPY is resistant to the feedback regulation of insulin elevation." (PMID 34307371, 2021). "However, we found that the deletion of MBOAT7 in liver does not lead to insulin resistance or altered insulin signaling in liver, as there was no change in the basal plasma glucose concentration." (PMID 32859645, 2021). "Additionally, IR KO in brown adipocytes results in an insulin secretion defect and a glucose intolerance but without insulin resistance, indicating a different metabolic impact of the insulin resistance in the BAT vs. WAT." (PMID 33435513, 2021). "Similarly, another study showed that beta-cell dysfunction and insulin resistance both are negatively connected to TSH, which may be explained by thyroid hormones' insulin-antagonistic properties combined with a rise in TSH." (PMID 35106234, 2021). "Given that T2DM is characterized by insulin resistance, hyperinsulinemia and impaired insulin signaling, it is not surprising that the increased GSK-3β activity in T2DM may lead to an increase in Aβ production and increase tau phosphorylation." (PMID 32326589, 2020).
Insulin resistance (continued). "In addition, fasting insulin level and HOMA-IR index significantly reduced after 8 weeks of andrographolide treatment, which was in accordance with metformin treatment, suggesting andrographolide prevents insulin resistance in diabetic mice." (PMID 32774682, 2020). "GDM develops if maximal insulin secretion does not match with insulin resistance." (PMID 32184821, 2020). "Moreover, our results showed that the glucose disposal was improved in GTT and ITT, moreover, FBG and HOMA-IR were markedly decreased, which strongly indicated that sesamol decreased insulin resistance rather than the insulin levels themselves." (PMID 31991934, 2020). "In the heart, chemerin has been shown to induce insulin resistance and apoptosis by decreasing AKT phosphorylation in neonatal rat cardiomyocytes, where chemerin, CMKLR1 mRNA, protein levels, and chemerin secretion are increased by TNFα and decreased by insulin." (PMID 33081064, 2020). "The neuronal glucose uptake may not depend on insulin totally, thus the concept of insulin resistance in the brain is more related to impaired insulin signaling pathways." (PMID 32365816, 2020). "From the values of fasting blood glucose and fasting plasma insulin, both obtained during oGTT performed in the last week of dietary intervention (time 0 – before glucose administration), we calculated HOMA-IR and HOMA-β indexes, which are mathematical models used to evaluate insulin resistance." (PMID 32283715, 2020). "At the time of GDM diagnosis, the divergence in analytes between groups was particularly striking; the Diet Group now showed a more favourable lipid profile than the women without GDM, in contrast to raised insulin resistance markers in the insulin-treated group." (PMID 32240196, 2020). "Moreover, it must be considered that not all obese patients have insulin resistance (about 25% of obese subjects are insulin sensitive, being classified, as we mentioned, into metabolically healthy obese), and remain insulin-sensitive for a period." (PMID 32858998, 2020). "The protective effect against insulin resistance appears to be independent of obesity as initial studies on Mgll−/− mice found that the mice could gain weight like WT mice but maintained insulin sensitivity to a greater extent." (PMID 33348740, 2020). "On the contrary, hepatic inflammation was significantly higher with FFD compared to HFD, and the observed systemic hyperinsulinemia during FFD may be due to hepatic insulin resistance rather than WAT insulin resistance." (PMID 32883049, 2020). "hs-CRP level has been shown to predict changes in insulin sensitivity and future insulin resistance even in non-diabetic adults; thus, hs-CRP level may indicate the imminent development of type 2 diabetes." (PMID 33679598, 2020). "Comparably, transgenic mice expressing a dominant-negative form of SHP2 showed insulin resistance in muscle and adipocytes, whereas tissue-specific reduction of SHP2 function in hepatocytes or adipocytes showed increased tolerance to insulin and high-fat diets." (PMID 32457793, 2020). "Also, erythrocyte ATP level correlated with the parameters of insulin resistance parameters: a negative correlation with insulin (r = −0.83; p = 0.001) and HOMA-IR (r = −0.81; p = 0.001) was observed for pre-exercise values." (PMID 32848864, 2020). "The positive correlations of these microRNAs with serum fasting glucose and HbA1c% and negative correlations with serum insulin levels (microRNA-486 and 15b) reflects their negative impact on the function of beta cells of Langerhans and/or insulin signaling pathway (i.e. insulin resistance)." (PMID 32988370, 2020). "Additionally, we did not assess hepatic insulin sensitivity based upon prior studies that only found FMT effects on peripheral insulin resistance." (PMID 32150549, 2020).